RELB (RELB proto-oncogene, NF-kB subunit)
Diseases named in the same sentence as RELB in open-access papers (continued):
Sharing a sentence is not in itself a finding about the gene and the disease.
infection (continued). "In addition to the cytokine and chemokine upregulation observed in this present work, the inflammatory response regulators SLAMF7, RELB, NFKBIZ, NFKBIA, and ZC3H12A were identified, further underlining the strong inflammatory response elicited by PCPEC during to infection." (PMID 33763387, 2021). "NF-κB (p65, RelB, c-Rel, NF-κB1, and NF-κB2) and MAPK (ERK, p38, and JNK) signaling pathways, as the downstream signals of TLR2 are essential immune molecules during infection that regulate the expression of inflammation cytokines." (PMID 37239946, 2023). "The non-canonical route is activated in HRSV-infected cells, and we have shown that genes involved in this pathway, including NFKB2, RELB, and NIK, are upregulated at later times post-infection." (PMID 32102364, 2020). "This was supported by the upregulation of the NF-kB inhibitor genes NFKBIA and NFKBIZ, the AP-1 transcription factor complex genes FOS, JUN, FOSB and JUNB as well as other NF-kB target genes such as TNFAIP3, RELB, NR4A2, DUSP1 and CD69 in response to infection." (PMID 37700317, 2023). "Infection with P. histicola resulted in the induction of RelB and p52 protein but not p65 or p50 protein, clearly indicating the induction of the alternative NF-κB pathway." (PMID 33031374, 2020). "Since we hypothesized that ECTV affects the level of phosphorylation of both RelB and p100, we assessed the level of phosphorylation of RelB at Ser552 and p100 phosphorylation at Ser872 upon ECTV infection of JAWS II DCs and RAW 264.7 macrophages." (PMID 33020446, 2020). "The NFκB complex consists of 5 proteins [NFκB1 (p105), NFκB2 (p100), RELA (p65), RELB and REL (c-Rel)] and, upon activation, provides a powerful defense mechanism against infection and stress; regulation of the complex in managed in part by families of NFκB inhibitor genes (IκB) and kinases (IKK)." (PMID 27078000, 2016). "In contrast, the p52/RelB subunits involved in non-canonical NF-κB signalling pathway were not activated in DV infection compared to mock infection of DCs." (PMID 25754930, 2015). "In the absence of infection, luciferase activity was decreased ~2-fold in cells treated with siRNAs against RelB, compared to the other siRNA-treated cells." (PMID 24206648, 2013). "(dark grey bars, RelB in bold) Infection with the virulent Y. pestis Ind195 strain produced no further change in luciferase expression (light grey bars, RelB), indicating that a basal level of luciferase activity had been reached in cells depleted of RelB." (PMID 24206648, 2013). "Since CMV infection induces the canonical (NF-κB1/RelA; NF-κB1/RelB) and noncanonical (NF-κB2/RelB) NF-κB pathways, we postulated that mCMV infection of E11 MANs would induce changes in NF-κB protein expression and localization." (PMID 18371224, 2008). "Interestingly, before infection, the expression levels of many of these master regulators (e.g., REL, NFKB1, RELB, IRF2, IRF9) were different across the three species, while post-infection, their expression converged to practically the same level, regardless of species." (PMID 21187902, 2010). "Infection with P. aeruginosa also induced significantly higher levels of nuclear p65-DNA binding (2 and 4 hours, p<0.001 and p<0.01) and significantly higher nuclear p50-DNA binding in response to infection (at 4 hours, p<0.001), but P. aeruginosa did not change nuclear RelB- or p52-DNA binding." (PMID 33031374, 2020). "We found that DDIT4, CTH, RELB, and SLC7A11, but not NDRG1 and CHAC1, increased in gastric tissues at 4 months post-infection (MPI)." (PMID 32457731, 2020). "In contrast, infection neither affected expression of key activators of the TLR pathway (IRAK1, MYD88, and RELA) nor RELB, a key element pivotal for DC differentiation, maturation, and MHC Class I-restricted presentation." (PMID 32582184, 2020). "Infection by WSN virus, similar to treatment with imiquimod, reduced the level of CYLD but not that of RelB." (PMID 29018444, 2017).
adenocarcinoma (5 papers, 2015 to 2022). A common cancer characterized by the presence of malignant glandular cells. "We showed that squamous tumors are devoid of nuclear NF-κB activity, whereas, consistent with our previous findings, the basal adenocarcinomas expressed high levels of nuclear alternative (p52/RelB) NF-κB." (PMID 35681213, 2022). "In this study, we systematically examined the biological significance of RelB in an adenocarcinoma cell line and NSCLC tissues." (PMID 29983639, 2018). "High RelB expression was detected in 53.3% (49/92) of the adenocarcinomas." (PMID 29983639, 2018). "Moreover, RelB was overexpressed in both mutant KRAS-induced hyperplastic lesions and adenocarcinomas." (PMID 26147201, 2015).
neurologic disease (2 papers, 2010 to 2021). "The current findings provide a theoretical and experimental basis, but the mechanisms of the hsa-miR-933/RELB/CCL21 regulatory axis in the development of HF and neurological disorders should be validated by cellular and animal experiments." (PMID 34595235, 2021). "Thus, hsa-miR-933, RELB, and CCL21 may be correlated with HF and neurological disorders." (PMID 34595235, 2021).
blood cancers (1 paper, 2016).
cardiovascular disease (1 paper, 2023). "According to previous reports, RELB, HAND1, and RELA are critical transcriptional factors in cardiovascular disease, and RELB and RELA have been confirmed to be related to AS progression." (PMID 37325477, 2023).
hematological cancers (1 paper, 2018). "While non-canonical NF-κB RELB signaling is described to be mostly present in hematological cancers, solid cancers reveal constitutive canonical NF-κB RELA or c-REL activity." (PMID 29673141, 2018). "While non-canonical NF-κB RELB signaling is described to be mostly present in hematological cancers, solid cancers reveal canonical NF-κB RELA (p65) and/or c-REL activity." (PMID 29673141, 2018).
infectious disease (1 paper, 2024). A disorder directly resulting from the presence and activity of a microbial, viral, or parasitic agent in humans. "By screening our in-house database of whole-exome sequencing (WES) data for over 25,000 patients with various infectious diseases, we identified a single patient (P1) carrying a biallelic private variant of RELB that was predicted to be deleterious." (PMID 39231201, 2024).
inflammation (1 paper, 2024). Aberrant reaction of the microcirculation characterized by movement of fluid and leukocytes from the blood into extravascular tissues. "Noteworthy, lung allergy can be resolved by the transfer of RelB-competent DCs suggesting that the expression of RelB in DCs is necessary to prevent lung inflammation in this setting." (PMID 39443450, 2024).
metabolic disease (1 paper, 2019). A congenital disorder (due to inherited enzyme abnormality) or acquired (due to failure of a metabolically important organ) disorder resulting from an abnormal metabolic process. "NF-kappaB, a transcription factor that has five subunits, namely p50, p52 RelA/p65, c-Rel and RelB, plays a critical role in inflammatory process and metabolic disease." (PMID 30926764, 2019).
neurodegenerative disease (1 paper, 2021). A disorder of the central nervous system characterized by gradual and progressive loss of neural tissue and neurologic function. "Our findings demonstrated that BMSCs promote remyelination in the spinal cord of HD-exposed rats via TNFα/RelB-Hes1 pathway, providing novel insights for evaluating and further exploring the therapeutical effect of BMSCs on demyelinating neurodegenerative disease." (PMID 34348774, 2021).
psychiatric disorder (1 paper, 2016). A disorder characterized by behavioral and/or psychological abnormalities, often accompanied by physical symptoms. "The NF-κB family of transcription factors, including p50, p52, RelA/p65, cRel and RelB, have been shown to play important roles in hippocampal neurogenesis and psychiatric disorders." (PMID 27877109, 2016).
RELB also shares sentences with these, for which no sentence is quoted: heart failure (3 papers); metastatic tumors (3); coronary heart disease (2); large cell carcinoma (2); malaria (2); multiple sclerosis (2); alcoholic liver diseases (1); allergic bronchopulmonary aspergillosis (1); alopecia (1); asthma (1); autoimmune hepatitis (1); bacterial infections (1); behavioral disorders (1); bladder cancer (1); carcinoid (1); cardiomyopathy (1); cervical cancer (1); Charcot-Marie-Tooth disease (1); chronic hepatitis C (1); clear cell renal carcinoma (1); congenital heart disease (1); cystitis (1); Diarrhea (1); dysplasia (1); Ectodermal dysplasia (1); endometrial cancer (1); fibrosis (1); Fundus dystrophy (1); gouty arthritis (1); hematological malignancies (1).
A further 28 diseases each share a sentence with RELB in 1 paper.